MIR642B (microRNA 642b)
Synonyms: hsa-mir-642b; mir-642b
Gene: MicroRNA gene on chromosome 19 (45,674,932 to 45,675,008, reverse strand). Ensembl gene ENSG00000283212.
Gene Ontology:
Biological process: miRNA-mediated post-transcriptional gene silencing
Cellular component: RISC complex